XAGE3 (X antigen family member 3)
Synonyms: XAGE-3; GAGED4; PLAC6; PP9012; CT12.3a; CT12.3b
Tractability: Antibody: the Human Protein Atlas places it where antibodies can reach.
Gene: Protein-coding gene on chromosome X (52,862,525 to 52,868,083, reverse strand). Ensembl gene ENSG00000171402.
Subcellular location (Human Protein Atlas): Vesicles; Plasma membrane
Gene Ontology:
Molecular function: protein binding
Homologues: Orthologues: chimpanzee XAGE3 (99% identical), macaque XAGE3 (86% identical). Paralogues in human: XAGE5 (73% identical), XAGE2 (72% identical), GAGE10 (56% identical), GAGE1 (51% identical), GAGE13 (51% identical), GAGE12C (50% identical), GAGE12D (50% identical), GAGE12E (50% identical), GAGE12F (50% identical), GAGE12G (50% identical), GAGE12J (50% identical), GAGE2A (50% identical), and 10 more.
Diseases named in the same sentence as XAGE3 in open-access papers:
XAGE3 is named in the same sentence as 6 diseases in open-access papers, as found by Europe PMC text mining. Sharing a sentence is not in itself a finding about the gene and the disease. The quoted sentences say what the papers report.
ovarian carcinoma (2 papers, 2015 to 2021). A malignant neoplasm originating from the surface ovarian epithelium. "In our previous study, some XCTAs, including XAGE3 and MAGEA4, were overexpressed in ovarian cancer with a loss of XCI." (PMID 26360551, 2015).
serous ovarian cancer (1 paper, 2021). "In the serous ovarian cancer patients of cohort 2 (n = 20/80), detectable antibodies (Z-scores > 0) were seen against CTAG2 (n = 3/20, 15%), SHARPIN (n = 2/20, 10%), PNMA2 (n = 2/20, 10%), MAGEB4 (n = 1/20, 5%), MRFAP1L1 (n = 1/20, 5%), SERPINB1 (n = 1/20, 5%) and XAGE3 (n = 1/20, 5%)." (PMID 34681879, 2021).
cancer (6 papers, 2013 to 2025). A tumor composed of atypical neoplastic, often pleomorphic cells that invade other tissues. "XAGE3 is part of a family of cancer/testis-associated antigens, although it is not expressed in either tumor or testis tissue, and its function is currently unknown." (PMID 29335024, 2018). "The expression of several cancer-testis antigens, including MAGE-A genes, XAGE3, and NY-ESO-1, is regulated by DNA methylation." (PMID 40141091, 2025). "XAGE3 and MAGEA4 belong to a family of cancer-testis antigens." (PMID 25742136, 2015).
tumor (4 papers, 2015 to 2021). "Further to this, XAGE3, S100P, CSH1, ErbB2, PAPPA1, EGLF6, COBLL1 were all identified as having potential roles in growth and development, whilst XAGE3, ErbB2, PAPPA1, EGLF6 have reported links to tumour growth." (PMID 31533811, 2019).
XAGE3 also shares sentences with these, for which no sentence is quoted: glioblastoma (2 papers); estrogen-receptor negative breast cancer (1).